CRP (C-reactive protein)
Diseases named in the same sentence as CRP in open-access papers (continued):
Sharing a sentence is not in itself a finding about the gene and the disease.
bacterial infection (continued). "Indeed, sensitivities and specificities of up to 90% have been shown for bacterial infections in individuals who present with CRP concentrations of 100 mg/L or more." (PMID 19351421, 2009). "Many geriatricians have the clinical impression that the CRP response to serious invasive bacterial infections may be delayed in frail old patients." (PMID 18706087, 2008). "However, elevated CRP may represent inflammatory conditions other than bacterial infection, and the sensitivity and specificity of CRP in predicting EOS may be low." (PMID 41441318, 2025). "Furthermore, CXCL10, along with Tumor necrosis factor-Related Apoptosis-Inducing Ligand (TRAIL) and CRP levels in the blood, forms a powerful host-derived signature for differentiating viral from bacterial infections, demonstrating a high AUC in the diagnosis and prognosis of these infections." (PMID 39861921, 2025). "However, most rickettsial cases demonstrate CRP < 150 mg/L and procalcitonin < 2 ng/mL, which may aid in distinguishing them from severe bacterial infections, where these inflammatory markers are typically more markedly elevated." (PMID 40864107, 2025). "Additionally, CRP is a well-known indicator of bacterial infections." (PMID 41059988, 2025). "CRP elevation was never associated with proven bacterial infection in our cohort." (PMID 41237095, 2025). "Diagnostic tools such as C-reactive protein (CRP) and procalcitonin (PCT) are commonly used to support clinical decision-making despite the ongoing debate on their sensitivity for potentially serious bacterial infections and utility in changing antibiotic prescribing." (PMID 41006994, 2025). "IL-1β, IL-6, IL-18, and tumor necrosis factor (TNF)-α are pro inflammatory cytokines, and procalcitonin (PCT) and C-reactive protein (CRP) are nonspecific markers of systemic inflammation that increase sharply during pathogenic infections including bacterial infections." (PMID 40532039, 2025). "However, CRP levels are slightly elevated during severe bacterial infections." (PMID 38962614, 2024). "However, it is important to consider other factors outside bacterial infection that could increase CRP, an acute phase reactant." (PMID 38773553, 2024). "In our study, sampling was performed in a relevant population of clinical CAP and the results confirm our hypothesis that the host-response biomarker signature in Mp CAP differs from levels observed during conventional bacterial infections, as previously observed for CRP and other biomarkers." (PMID 38092364, 2024). "Also, the specificity of CRP appeared to be slightly reduced among HIV positive children, a phenomenon potentially attributable to their heightened risk of other bacterial infections, which could also cause increased CRP levels." (PMID 39446791, 2024). "Additionally, we evaluated the diagnostic efficiency of PCT and CRP in distinguishing between Gram-positive (GP) and Gram-negative (GN) bacterial infections." (PMID 38172766, 2024). "These values are significantly higher (p<0.0001) than most other biomarkers used commonly to predict bacterial infection (PCT at 0.74, WBC at 0.56, ANC at 0.42), suggesting that CRP may currently be the best biomarker for predicting bacterial infection in lower resource settings." (PMID 37478118, 2023). "Reductions in proinflammatory markers C-Reactive protein (CRP), interleukin – 6 (IL6) and tumor necrosis factor-α (TNFα) and increments in anti-inflammatory markers (interleukin – 4 (IL4)) were associated with an improvement in CSDD and MSEE in patients recovering from a bacterial infection." (PMID 37762523, 2023). "Indeed, elevated CRP levels are observed not only in pediatric patients infected with adenovirus in the absence of a secondary bacterial infection but also in patients with bacterial infections." (PMID 38109177, 2023).
bacterial infection (continued). "Likewise, the baseline level of CRP is low in the sera of healthy individuals (< 1 mg/dL), but CRP increases several folds and can even reach > 25 mg/dL in response to severe bacterial infection and inflammation insults, with an onset of 12–24 h, and a 20–72 h plateau." (PMID 35149284, 2022). "However, while CRP is highly sensitive, it is less specific for detecting bacterial infection." (PMID 36670590, 2022). "We then tested the performance of CRP, IL-6, and IL-10 to predict bacterial infection; the AUCs of CRP, IL-6, and IL-10 were 0.614 (95% CI, 0.531–0.697), 0.703 (95% CI, 0.626–0.780), and 0.657 (95% CI, 0.577–0.737), indicating IL-6 was the most powerful biomarker to predict bacterial infection." (PMID 35391735, 2022). "Moreover, in the event of bacterial infection, the concentration of CRP in plasma could increase by up to 1000-fold." (PMID 35432153, 2022). "In that scenario, patients with an elevated CRP are more likely to be considered suffering from a bacterial infection and therefore be admitted and started on early antibiotic treatment, while patients with a low CRP may be more easily discharged or have a delay in treatment." (PMID 35897672, 2022). "However, we found that considering the time from onset of symptoms improved CRP performance, and changed the optimal test cut-off value: CRP > 1.5 mg/dL obtained > 6 hours from symptoms onset improved the area under the ROC curve to 0.87 and had 100% sensitivity to diagnose bacterial infections." (PMID 36517750, 2022). "The ability of PCT, CRP and PCT or CRP combined with clinical symptoms to discriminate between viral and bacterial infection were assessed by portraying receiver operating characteristic (ROC) curves among patients with only a viral or a typical bacterial infection." (PMID 34583675, 2021). "The aim of the present study was to assess whether PCT or CRP combined with clinical characteristics could distinguish between viral and bacterial infections using comprehensive and sensitive methods of etiologic classification in hospitalized non-intensive care unit (ICU) adults with LRTIs." (PMID 34583675, 2021). "But whether PCT or CRP could distinguish viral or bacterial infection is a controversial issue." (PMID 34583675, 2021). "In addition, indicators of inflammation, bacterial infection and blood coagulation, including procalcitonin (0.166 ng/mL vs. 0.076 ng/mL, P < 0.001), C-reactive protein (CRP; 107.3 vs. 37.65, P < 0.001), and D-dimer (6.32 vs. 1.09, P < 0.001), showed a higher level in the non-survivors." (PMID 34399679, 2021). "Furthermore, CRP was considered to be useful to assess the severity of some bacterial infections." (PMID 34362428, 2021). "PCT is a specific marker for bacterial infections and may not best reflect the inflammatory status (including chemical inflammation caused by pancreatic fistula) unlike CRP." (PMID 33784995, 2021). "Infections are almost always self-limiting in immunocompetent patients, but the severe systemic presentation combined with laboratory alterations such as elevation of white blood cell (WBC) count with neutrophilic prevalence and of C-reactive protein (CRP) may suggest a bacterial infection." (PMID 34578465, 2021). "CRP was associated with poor outcome in this age group, but neither this nor procalcitonin differed between the age categories, suggesting that bacterial infection may not be a greater driver of disease in older patients." (PMID 32586323, 2020). "In addition, we found that leukocyte elevation, neutrophil elevation, and C-reactive protein elevation were more common in severe and critical patients, which indicated that severe and critical patients may be more prone to secondary bacterial infection." (PMID 33062082, 2020).
bacterial infection (continued). "Therefore, the aims of this secondary analysis are to evaluate the performance of DLL1 to diagnose bacterial infection as well as to predict a complicated clinical course of patients following liver transplantation compared to standard biomarkers such as PCT or CRP." (PMID 33142943, 2020). "Prior attempts to determine whether inflammatory markers such as C-reactive protein or procalcitonin, white blood cell count values or percent of immature neutrophils can reliably distinguish bacterial infection in a pediatric ICU population, have found mixed results." (PMID 32616046, 2020). "Likewise, use of a rapid CRP test could help distinguish viral from bacterial infections and reduce antibiotic prescription rates significantly, as was recently shown in a study in northern Vietnam." (PMID 33147269, 2020). "However, it should also be noted that the accompanying low specificities (42.3% for PCT, 40.4% for CRP) and high rates of false positive may arise if cut-off values of PCT and CRP with 100% sensitivity are used as markers for diagnosing bacterial infection." (PMID 31777354, 2019). "Third, CRP and procalcitonin concentrations may have been reduced in participants with bacterial infections by antibiotic treatment prior to providing a blood specimen at study enrolment, which would reduce the ability of the biomarkers to discriminate CAP from TB and PJP." (PMID 30107791, 2018). "Therefore, it was suggested that this cytokine could increase earlier than CRP during bacterial infection and that it could enable an earlier diagnosis." (PMID 29675434, 2018). "Although observational studies have shown that PCT is more sensitive and specific for bacterial infections in comparison to CRP, and prospective trials have investigated the reduction of antibiotics in patients with respiratory complaints, the role of PCT in the ED remains unclear." (PMID 27048405, 2016). "In addition to a medical evaluation, one possible course of action may be to perform analysis of C- reactive protein (CRP) directly at the NH, as the CRP level rises rapidly in response to inflammatory stimuli, especially bacterial infections." (PMID 26459627, 2015). "The guidelines for antibiotic treatments in primary care give some advice for what level of CRP to suspect bacterial infections in lower respiratory infections but for throat symptoms the guidelines recommend a strep A test, so according to this there seem to be an overconsumption of CRP." (PMID 26585447, 2015). "However, a multiplexed pattern of results consisting of the combined interpretation of low CRP, high CRP, and elevated levels of MxA may provide a sensitive and specific way to identify an immune response to a viral and/or bacterial infection." (PMID 26672961, 2015). "A single CRP test will not be very indicative of bacterial infection but a combination of neutrophil, IG and CRP may provide more valid information considering the complex relationship between the antibiotic use and the clinical features of bacterial infection." (PMID 24764729, 2014). "Moreover, the majority of the ordered CRP tests did not have a solid evidence base to support their use as diagnostic tools for the accurate detection of bacterial infections." (PMID 22943554, 2012). "Finally, we did not assess the diagnostic value of Procalcitonin, a relatively new marker for bacterial infections, although it might be a better test than the C-reactive protein to identify patients who should be treated with antibiotics." (PMID 21569472, 2011). "Thus, it is plausible that the high CRP levels among some of the patients in the current study may represent a secondary bacterial infection." (PMID 20920320, 2010). "Thus, a diminished or delayed CRP response to bacterial infections in the old may be biologically plausible." (PMID 18706087, 2008). "It is poorly known whether CRP in bacterial infection is age-dependent." (PMID 18706087, 2008).
bacterial infection (continued). "IL-6 levels rise earlier than CRP levels, and thus indicate inflammation sooner, while PCT has higher specificity for bacterial infections." (PMID 41334533, 2026). "In the diagnosis of sepsis, the combined use of CRP and PCT is more advantageous than the use of either marker alone, as it enables early identification of bacterial infections and helps in assessing clinical prognosis." (PMID 40160471, 2025). "constructed a predictive nomogram for pulmonary necrosis using variables such as MP combined with bacterial infection, chest pain, LDH, CRP, duration of fever, and D-dimer." (PMID 40171163, 2025). "Upon admission, laboratory tests painted a picture of a severe bacterial infection, with a markedly elevated PCT of 1.01 ng/mL, an HBP level of 207.89 ng/mL, and a CRP of 16.2 mg/L." (PMID 41143408, 2025). "While C-reactive protein (CRP) and procalcitonin (PCT) are the most commonly used biomarkers for diagnosing bacterial infections, both have several limitations." (PMID 40351994, 2025). "In 110 ICU patients’ plasma, calprotectin was evaluated as an early marker of bacterial infections and compared with PCT, CRP, and WBC." (PMID 40650251, 2025). "Bacterial infection and septic shock were supported by bilateral tonsil enlargement, elevated WBC, NEU%, CRP and PCT." (PMID 41551517, 2025). "The performance of calprotectin in the detection of bacterial infections was comparable to the performance of both PCT and CRP, and superior to the WBC count." (PMID 40650251, 2025). "Currently, the early clinical differentiation between viral and bacterial infections largely relies on symptomatology, WBC counts, and markers like CRP and PCT." (PMID 40046054, 2025). "Compared with patients with bacterial infections, patients with SFTS tended to have lower white blood cell (WBC) count, neutrophils (NEU), CRP, PCT, blood urea nitrogen (BUN), prothrombin time (PT), and fibrinogen levels." (PMID 39688402, 2025). "The AUC values of CRP, PCT, NC and NLR for diagnosing bacterial infections in NSCLC patients after chemotherapy received comparison, illustrating statistical significance (P<0.05)." (PMID 41281267, 2025). "Comparison of predictive value of CRP, PCT, NC and NLR levels in diagnosing bacterial infections in NSCLC patients after chemotherapy." (PMID 41281267, 2025). "HNL outperformed CRP and PCT in the distinction between viral and bacterial infections in an observational study in hospitalized patients with signs and symptoms of acute infection." (PMID 40598497, 2025). "Clinically, CRP, TNF-α, and IL-6 are utilized to assess inflammatory responses, with CRP produced by hepatocytes in response to inflammation and TNF-α and IL-6 playing roles in immune cell activation and serving as key indicators of bacterial infection." (PMID 40005662, 2025). "Biomarkers, including C-reactive protein (CRP), procalcitonin (PCT), and interleukin-6 (IL-6), in the bacterial infection group exhibited significantly elevated levels relative to the healthy controls (P < 0.0001)." (PMID 40046054, 2025). "Biomarkers play a potential key role in achieving accurate diagnosis, and traditional biomarkers such as CRP levels, serum PCT levels, and white blood cell count (WBC) have been widely used for bacterial infection diagnosis." (PMID 40661134, 2025). "On the other hand, current guidelines emphasize the importance of maintaining a high index of clinical suspicion for bacterial infection and recommend procalcitonin (PCT) and C-reactive protein (CRP) as biomarkers of infection." (PMID 41354872, 2025). "The accuracy of diagnosis using PCT level was higher compared with that using CRP levels among patients hospitalized for suspected bacterial infections; however, cost-effective analyses are necessary for encouraging the use of PCT instead of CRP measurements." (PMID 38525743, 2024).
bacterial infection (continued). "Compared to other well-established inflammation biomarkers, such as C-reactive protein (CRP) or procalcitonin (PCT), presepsin is believed to be a better detector of bacterial infection due to its direct involvement in relevant pathogenetic pathways." (PMID 39335474, 2024). "In the group of patients with bacterial infections, there were significantly higher levels of NLR, PLR, PCT, CRP, and absolute neutrophil count (ANC) compared to those with non-infectious diseases (p<10-6) (seeTable 2)." (PMID 39296886, 2024). "Changes in WBC, CRP, NLR, LMR, PLR, and WBCCRP were statistically significant between the influenza B group, the bacterial infection group, and the normal control group." (PMID 38306568, 2024). "The diagnostic performance evaluation of the four markers, namely CRP, PCT, NLR, and PLR, was conducted to predict bacterial infections in patients with clinical symptoms." (PMID 39296886, 2024). "There were statistically significant differences for CRP, LMR, PLR, and WBC × CRP between the influenza B group, the bacterial infection group, and the normal control group." (PMID 38306568, 2024). "Inflammatory markers (PCT, CRP, white blood cells, neutrophils, and NLR) were significantly higher in bacterial infection cases (p < 0.0001)." (PMID 39296886, 2024). "Patients with suspected bacterial infection were 9.3 times more likely to obtain CBC test (OR 9.31, 95% CI 1.24 to 69.72, p = 0.030) and 8.5 times more likely to obtain a CRP test (OR 8.57, 95% CI 1.14 to 64.36, p = 0.037)." (PMID 38786268, 2024). "Infected patients with secondary bacterial infections had significantly higher PCT and hs-CRP levels compared to their initial admission." (PMID 38576608, 2024). "Patients with a longer duration of fever and a physician‘s suspicion of bacterial infection were more likely to receive CBC, CRP, and/or urinalysis tests (p < 0.05)." (PMID 38786268, 2024). "Various inflammatory markers, including procalcitonin (PCT), C-reactive protein (CRP), erythrocyte sedimentation rate (ESR), and interleukin-6 (IL-6), have been investigated for diagnosing bacterial infections." (PMID 38297213, 2024). "Among the blood tests, WBC, CRP, and procalcitonin (PCT) are broadly used for the evaluation of bacterial infection." (PMID 38397360, 2024). "As expected, the amount of C-reactive protein in mouse serum was also significantly lower on day 7 in mice treated with HMAPH + dual light compared with PBS treatment, indicating the recovery of bacterial infection." (PMID 39323765, 2024). "Focusing on the group with a bacterial infection, comparison between OPG and CRP showed that CRP was more specifically increased compared to OPG." (PMID 38509997, 2024). "In patients with non-bacterial infection, CBC and CRP tests were prescribed in 72.4% (n = 268) and 73.8% (n = 273) of cases, respectively, and urinalysis were administered for almost a quarter (n = 92, 24.9%) of patients." (PMID 38786268, 2024). "Comparison of WBC, CRP, NLR, LWR, PLR, and WBC × CRP between different gender and age in bacterial infection group." (PMID 38306568, 2024). "Serum CRP and PCT levels are lower after MP infection than after bacterial infection; however, they help predict severe MPP." (PMID 38655275, 2024). "For this reason, PCT has been found to be a more specific biomarker for bacterial infections while WBC and CRP are rather unspecific inflammatory markers." (PMID 39609770, 2024). "CRP, PCT levels were significantly higher in bacterial infections compared to the IPA group in our study." (PMID 38633749, 2024). "CRP, ESR, and ferritin were the highest in patients with bacterial infections compared to controls (p < 0.001)." (PMID 39336155, 2024). "Investigating potential biomarkers, IL-6 and C-reactive protein (CRP) were scrutinized, alongside PCT, which emerged as another biomarker due to its elevation in bacterial infections." (PMID 39768616, 2024).